HEMK1 (HemK methyltransferase 1, mitochondrial release factors N(5)-glutamine)
Description:
N5-glutamine methyltransferase responsible for the methylation of the glutamine residue in the universally conserved GGQ motif of the mitochondrial translation release factors MTRF1, MTRF1L, MRPL58/ICT1 and MTRFR.
Synonyms: HEMK; MTQ1; MPRMC
Tractability: No criterion of Open Targets' tractability assessment is met for any kind of drug.
Gene: Protein-coding gene on chromosome 3 (50,567,895 to 50,596,168, forward strand). Ensembl gene ENSG00000114735.
Subcellular location: Mitochondrion
Gene Ontology:
Molecular function: peptide chain release factor N(5)-glutamine methyltransferase activity; protein binding; protein-glutamine N-methyltransferase activity; DNA binding; methyltransferase activity; N-methyltransferase activity; nucleic acid binding; protein methyltransferase activity; S-adenosylmethionine-dependent methyltransferase activity
Biological process: translational termination
Cellular component: mitochondrion
Genetic constraint (gnomAD): Loss-of-function variants: 32 observed, 44.86 expected, observed/expected ratio (o/e) 0.71, 90% interval 0.54 to 0.96. The upper end of that interval is the gene's LOEUF score, 0.96, which puts it in group 4 of 6, group 1 being the genes least tolerant of losing a copy. Missense variants: 379 observed, 451.34 expected, observed/expected ratio (o/e) 0.84, 90% interval 0.77 to 0.91. Synonymous variants: 153 observed, 172.63 expected, observed/expected ratio (o/e) 0.89, 90% interval 0.78 to 1.01.
Homologues: Orthologues: chimpanzee HEMK1 (99% identical), macaque HEMK1 (95% identical), dog HEMK1 (85% identical), rabbit HEMK1 (83% identical), pig HEMK1 (82% identical), guinea pig HEMK1 (80% identical), mouse Hemk1 (79% identical), rat Hemk1 (79% identical), tropical clawed frog hemk1 (47% identical), zebrafish hemk1 (41% identical), Drosophila melanogaster HemK1 (32% identical). Paralogues in human: HEMK2 (15% identical), ETFBKMT (11% identical).
Diseases named in the same sentence as HEMK1 in open-access papers:
HEMK1 is named in the same sentence as 7 diseases in open-access papers, as found by Europe PMC text mining. Sharing a sentence is not in itself a finding about the gene and the disease. The quoted sentences say what the papers report.
breast carcinoma (1 paper, 2023). "Interestingly, in the NSABP B-4 study, which also employed the gene expression panel nCounter® Breast Cancer 360TM, the HEMK1 gene was also described as a biomarker of pCR21." (PMID 38049525, 2023).
cancer (1 paper, 2014). A tumor composed of atypical neoplastic, often pleomorphic cells that invade other tissues. "Others like GRASP, HEMK1, RARB and SLC16A5 were methylated mostly in histologically detectable cancer and may represent later events." (PMID 25548652, 2014).
HEMK1 also shares sentences with these, for which no sentence is quoted: bacteremia (1 paper); COVID-19 (1); infection (1); parasitic infection (1); Sepsis (1).